GATA3 (GATA binding protein 3)
Diseases named in the same sentence as GATA3 in open-access papers (continued):
Sharing a sentence is not in itself a finding about the gene and the disease.
pancreatic cancer (13 papers, 2009 to 2026). "EUS-guided biopsy confirmed metastatic UC with concordant immunohistochemistry (GATA3+), excluding primary pancreatic cancer." (PMID 41893442, 2026). "In another study, both GATA3 and GATA6 were found to be upregulated in pancreatic cancer, with GATA3 expression closely associated with immune cell infiltration signatures, highlighting its potential role in modulating the tumor microenvironment." (PMID 41514651, 2025). "A predominant Th2 (GATA3+) over Th1 (T-BET+) cell infiltration is detectable in pancreatic cancer and an increased ratio of GATA3+/T-BET+ tumor-infiltrating lymphocytes associated with disease progression, indicating a pathogenic shift towards a Th2 response." (PMID 33022971, 2020). "Quantitative PCR (qPCR) analysis of the TFs revealed upregulation of Gata3 in both mouse lung and pancreatic cancer cell lines after TGF-β treatment for 3 hours, while no consistent upregulation in the 2 cell lines was found for the remaining TFs." (PMID 31874105, 2020). "In particular, in the presence of systemic TSLP, spontaneous pancreatic tumors transferred to K14-TSLPtg mice grew less than those in WT mice, with a significant increase in GATA3+ Th2 infiltrating cell numbers." (PMID 30214685, 2018). "A study on pancreatic cancer, in which a Th2 (GATA3+) cellular infiltrate is predominant, identified a central role for cancer-associated fibroblasts (CAFs) in conditioning DCs with Th2-polarizing capability, via TSLP secretion." (PMID 30214685, 2018). "Therefore, the presence of GATA-3+ lymphoid cells, which we observed in the pancreatic tumor microenvironment, might further contribute to fibrosis and local treatments aimed at reducing the presence of Th2 cytokines might be beneficial." (PMID 19798410, 2009). "GATA3/Tbet ratio and TH2 infiltrates were proposed as an independent prognostic factor for pancreatic cancer patients treated by surgery." (PMID 27782813, 2016). "The number of T-bet (+) T cells significantly increased in patients who received NAT p < 0.001) whereas GATA-3 and ROR-γt (+) lymphocytes were both minor populations in the pancreatic cancer microenvironment; therefore, it was difficult to compare the histological changes (data not shown)." (PMID 40612871, 2025). "We previously reported that pancreatic cancer patients have a selective Th2 skew in the anti-carcinoembryonic antigen (CEA) CD4+ T cell immunity, which correlates with the presence of a predominant GATA-3+ tumor lymphoid infiltrate." (PMID 19798410, 2009). "In this case, the negative GATA3/GCDFP-15 and positive pancreatobiliary profile in the pancreatic tumor were pivotal." (PMID 41229501, 2025).
T-cell lymphomas (13 papers, 2016 to 2025). "More specifically, the genetic landscape [e.g., PTEN loss, c-Myc amplifications] and signaling pathways [e.g., the T-cell receptor] characteristic of GATA-3 driven T-cell lymphomas are associated with significant translational output and hyperactive RiBi." (PMID 41309546, 2025). "The dysregulation of GATA3 is implicated in a wide spectrum of diseases, ranging from cancers, including breast, prostate, and T-cell lymphomas, to autoimmune and neurodegenerative disorders." (PMID 39768217, 2024). "The transcription factor GATA-3 regulates the growth and proliferation of both immature and mature T cells and has recently been implicated in T-cell neoplasms, including the most common mature T-cell lymphoma observed in much of the Western world." (PMID 36329027, 2022). "As prior studies have suggested that GATA-3 expressing mature T-cell lymphomas may be ontologically derived from Th2 cells, we examined the relationship between the GATA-3 target genes we identified and those associated with differentiated subsets of CD4 + T cells." (PMID 36329027, 2022). "Collectively then, we have identified novel and complementary GATA-3 dependent and independent mechanisms by which CDK9 regulates the growth and survival of GATA-3 driven T-cell lymphomas." (PMID 41309546, 2025). "The transcription factor GATA-binding protein 3 (GATA-3) regulates oncogenic transcriptional programs across diverse T-cell lymphomas, including subsets of both peripheral and primary cutaneous T-cell lymphomas." (PMID 41309546, 2025). "PI3K/AKT and c-Myc activation, as observed in GATA-3 driven T-cell lymphomas, likely promote ribosome biogenesis." (PMID 41309546, 2025). "Among GATA-3 dependent T-cell lymphomas, the GATA-3 dependent transcriptome includes receptors, kinases, and transcription factors that play a central role in oncogenic signaling pathways, including those associated with T-cell receptor and PI3K/AKT signaling." (PMID 41309546, 2025). "In the PTCL, NOS and the GATA-3+ subclass of T-cell lymphomas resembled CTCL on a molecular level in which type 2 cytokines have a direct role in the proliferation and survival of tumor cells." (PMID 37746258, 2023). "In a previous genomic study, Heavican observed the same pattern of CNV aberration mainly in GATA3 T-cell lymphoma." (PMID 35464471, 2022). "Collectively, these findings are consistent with previous studies suggesting that GATA-3 confers chemotherapy resistance in mature T-cell lymphomas." (PMID 36329027, 2022). "T cell receptor signaling has been reported to play a role in the progression of extranodal NK/T cell lymphoma and to activate the ITK/NF-κB/GATA-3 axis to promote chemoresistance in T cell lymphomas." (PMID 33766042, 2021). "In T-cell lymphoma GATA3 and MIR17HG are overexpressed while in early T-cell progenitor ALL these genes are inactivated or downregulated." (PMID 29746601, 2018). "GATA3 is expressed in 33–45% of peripheral T cell lymphomas and a subset of T cell lymphomas that correlated with poor survival was found to have increased GATA3 expression." (PMID 27588406, 2016). "Therefore, CDK9 is a therapeutic vulnerability across genetically and transcriptionally diverse T-cell lymphomas, including those for which GATA-3 is oncogenic." (PMID 41309546, 2025). "Additionally, the altered expression of GATA3 contributes to the worsening of disease progression in hematological malignancies, such as T-cell lymphomas." (PMID 39768217, 2024). "In contrast, most T-cell lymphomas share morphological similarities and feature different frequencies of genetic alterations that either amplify the T-cell receptor signaling (e.g., NF-kB, RhoA, GATA3) or bypass it entirely (e.g., JAK/STAT, Pi3K)." (PMID 36605429, 2022). "FAT1 mutations spanned over the two main GATA3/TBX21 subgroups of peripheral T-cell lymphomas not otherwise specified." (PMID 31028364, 2020).
T-cell lymphomas (continued). "Two clinical studies showed that GATA3 is aberrantly overexpressed in a subset of T cell lymphomas." (PMID 27588406, 2016). "We deduced that GATA3 plays a similar role in the regulation of cytokines in T cell lymphoma." (PMID 27589565, 2016). "In transgenic mice, forced expression of GATA3 during T cell development induced T cell lymphomas." (PMID 27588406, 2016). "Overexpression of GATA3 in T cells induces T cell lymphomas in mice." (PMID 27588406, 2016). "Consequently, CDK9 antagonism, by impairing rRNA processing, rapidly culminates in nucleolar stress, and the subsequent termination of RiBi, providing a novel MCL-1 independent mechanism by which CDK9 antagonism is a therapeutic vulnerability in GATA-3 dependent T-cell lymphomas." (PMID 41309546, 2025). "We had previously shown that GATA-3 is oncogenic in this GEM model and demonstrate here that these T-cell lymphomas are MCL-1 independent." (PMID 41309546, 2025). "Therefore, GATA-3 dependent and GATA-3 independent transcripts collaboratively promote RiBi in T-cell lymphomas by promoting rRNA transcription and processing, respectively." (PMID 41309546, 2025). "Therefore, we sought to examine the extent to which CDK9 antagonism is a therapeutic vulnerability in vivo using a GATA-3 dependent, but MCL-1 independent, T-cell lymphoma model." (PMID 41309546, 2025). "CDK9 dependent transcriptional programs that are not dependent on GATA-3 may be significantly enriched in GATA-3 dependent T-cell lymphomas." (PMID 41309546, 2025). "Recently, it has been found that in non-Tfh-derived T-cell lymphomas like PTCL-NOS, gene regulators like t-bet, GATA-3, and FoxP3 regulate the differential expression of their target genes including those cytokines that regulate the constituents of the TME." (PMID 37746258, 2023).
hepatocellular carcinoma (12 papers, 2016 to 2025). A malignant tumor that arises from hepatocytes. "Also, KIAA1429 mediated the m6A methylation of GATA3 pre-mRNA, which caused altered GATA3 expression and malignant phenotypes of hepatoma cells." (PMID 35217651, 2022). "Upregulation of KIAA1429 expression in hepatocellular carcinoma induces m6A modification on pre-mRNA of GATA3, leading to increased tumor cell proliferation and metastasis." (PMID 37474926, 2023). "Conversely, carcinomas with low GATA3 expression are positive in less than 10% of cases, including gastric and colorectal adenocarcinoma, endometrial adenocarcinoma, hepatocellular carcinoma, cholangiocarcinoma, prostatic adenocarcinoma, and thyroid carcinoma." (PMID 37629741, 2023). "It has been reported that KIAA1429 mediated the m6A methylation of its direct downstream target GATA binding protein (GATA3), and thereby facilitating the malignant phenotypes of hepatoma cells." (PMID 33796449, 2021). "In hepatocellular carcinoma, GATA3 has been identified as a direct downstream target of the KIAA1429-mediated m6A modification." (PMID 34422053, 2021). "In hepatoma cells, athough it seems that HBx-induced GATA3/2 activation and Ap-1 or SP-1 activation might results in opposite effect on MICA expression, we indeed observed that HBx suppresses MICA expression in our experiments." (PMID 27528231, 2016). "However, whether GATA-2 and GATA-3 are involved in MICA/B expression in hepatoma cells is still unknown." (PMID 27528231, 2016).
invasive ductal carcinoma (12 papers, 2016 to 2025). "We therefore tested our findings in organoids derived from three ER-positive invasive ductal breast carcinoma patients, a primary tumor, a bone metastasis harboring GATA3 frameshift mutations (primary: p.H433fs and metastasis: p.S410fs) and one bone metastasis carrying wild-type GATA3." (PMID 35440675, 2022). "A punch biopsy was acquired from the largest scalp lesion on 15 September 2022, and showed metastatic invasive ductal carcinoma with positive ER (95%), PR (5%), cytokeratin-7 (CK-7), and GATA binding protein 3 (GATA-3)." (PMID 37198611, 2023). "This cell line is representative of estrogen receptor positive (ER+) invasive ductal breast carcinoma, which is known to be mainly driven by the combined activity of the TFs ESR1, GATA3, and FOXA1." (PMID 34174819, 2021).
peripheral T-cell lymphoma (12 papers, 2015 to 2024). "High expression of GATA3 identifies a biologically distinct subgroup in peripheral T cell lymphoma associated with overall poor prognosis." (PMID 26445707, 2015). "The gene expression profile of the GATA3 subset of peripheral T cell lymphoma also identifies high expression of Th2 associated transcripts." (PMID 26445707, 2015). "Importantly, GATA3 was regarded as a highly breast-specific immunomarker, especially for ER-negative metastatic breast carcinomas, and it was also used to identify a high-risk subset of peripheral T-cell lymphomas." (PMID 27528231, 2016). "Despite being unreported in DLBCL so far, GATA-3 positivity is observed in classic Hodgkin lymphoma (cHL) and in a subset of peripheral T-cell lymphoma; in particular, GATA-3 expression correlates with poor prognosis in peripheral T-cell lymphoma." (PMID 35200580, 2022). "Based on gene expression profiling, Amador and colleagues recently assessed Th1 (Tbet and CXCR3) and Th2 (GATA3 and CCR4) protein expression using the IHC algorithm in cases of nodal and extranodal peripheral T-cell lymphoma, not otherwise specified (PTCL, NOS)." (PMID 38474383, 2024). "In peripheral T-cell lymphoma, not otherwise specified, (PTCL, NOS) two molecular subtypes have been identified with the help of gene expression profiling studies: PTCL-GATA3 and PTCL-TBX21, characterized by overexpression of the transcription factors TBX21 or GATA3." (PMID 38835969, 2024).
Insulin resistance (11 papers, 2011 to 2025). Increased resistance towards insulin, that is, diminished effectiveness of insulin in reducing blood glucose levels. "GATA3-associated impaired adipogenesis affects lipid homeostasis contributing to body fat distribution, causing the deposition of ectopic fat in the liver, kidney, and skeletal muscles; triggering insulin resistance; and increasing the risk of T2D." (PMID 36232443, 2022). "Other studies have suggested the GATA3′s crucial function as a gatekeeper of terminal adipocyte differentiation, and that its inhibition may reverse the impaired adipogenesis and linked insulin resistance." (PMID 36232443, 2022). "This growing body of evidence highlights the potential of GATA-3 as a therapeutic target for obesity-related metabolic disorders, including insulin resistance and type 2 diabetes." (PMID 39851528, 2025). "In contrast, GATA3 suppresses PPAR-γ, inhibits adipogenesis, and has been implicated in insulin resistance." (PMID 41573201, 2025). "The suppression of GATA-3 has also shown promising results in reducing inflammation and reversing insulin resistance in vivo." (PMID 39851528, 2025). "The coordinated upregulation of the antagonistic regulators GATA3 and PPARγ in thigh fat during insulin resistance points to a complex, adaptive response aimed at maintaining adipocyte function and systemic lipid homeostasis." (PMID 41573201, 2025). "First, the blockade of IL-1 improves glycemia and β-cell secretory function; repression of the IL-6 receptor relieves diabetic renal injury and insulin resistance, and suppression of GATA-3 restores insulin sensitivity." (PMID 36776877, 2023). "IL-1, IL-6, IL-17, IL-33, GATA-3, and other proinflammatory cytokines also play important roles in renal insulin resistance." (PMID 36776877, 2023). "GATA Binding Protein 3 (GATA3) is implicated in impaired adipogenesis and the onset of insulin resistance." (PMID 36232443, 2022). "These limitations must be addressed in future studies using diseased models with insulin resistance to explore the effect of GATA3 inhibition effect on reversing IR in vivo." (PMID 36232443, 2022). "Regarding T2D, GATA3 is considered an anti-adipogenic factor and a potential molecular therapeutic target for insulin resistance, through restoration of adipogenesis and amelioration of inflammation." (PMID 34502231, 2021). "It has been noted that there is a link between nutritional changes and GATA3 protein, as it can alter adipogenesis and lead to insulin resistance, and inhibition of GATA3 has been shown to modify impaired adipogenesis and contribute to restoring healthy fat distribution." (PMID 40421094, 2025). "Together, these findings highlight the important role GATA3 plays in the development of impaired adipogenesis and insulin resistance, therefore blocking GATA3 could reverse these mechanisms and enhance both adipogenesis and insulin signaling." (PMID 36232443, 2022). "Thus, due to association with a large number of SNPs and regulatory motifs, rs3824662 may alter the expression pattern of the GATA3 gene, which in turn may affect regulatory T cells, followed by onset of type 2 diabetes through developing insulin resistance." (PMID 30044774, 2018). "Decreased GATA3 expression in the SVF of obese mice and humans indicates a decrease in TH2 cells with the development of insulin resistance." (PMID 21298111, 2011). "Our data therefore suggest the potential utilization of GATA-3 modulation for preventing the development of insulin resistance in non-obese as well as obese individuals." (PMID 36232443, 2022). "Our findings also showed that exposure to 4-HNE, a reactive aldehyde known to increase inflammation, oxidative stress, and insulin resistance in preadipocytes, increased TNF-α levels in non-targeted, but not in GATA-3 knockout, cells." (PMID 39851528, 2025).
pulmonary fibrosis (11 papers, 2010 to 2025). Chronic progressive interstitial lung disorder characterized by the replacement of the lung tissue by connective tissue, leading to progressive dyspnea, respiratory failure, or right heart failure. "miR-205 attenuates bleomycin-induced pulmonary fibrosis in rats by inhibiting the activation of the ER stress signaling pathway through targeting GATA binding protein 3 (GATA3)." (PMID 41329539, 2025). "Th2 cells, regulated by the GATA-binding protein 3 (GATA3), can secrete interleukin-4 (IL-4) and promote pulmonary fibrosis in the later fibrotic stage." (PMID 37828528, 2023). "More importantly, HDAC3 played a pivotal role in mediating EMT in AT2 cells and pulmonary fibrosis by deacetylating GATA3 and inhibiting its degradation." (PMID 37951958, 2023). "TGF-β1/SMAD3 directly promoted the transcription of HDAC3, which aggravated EMT in AT2 and pulmonary fibrosis in mice via deacetylation of GATA3 and inhibition of its degradation." (PMID 37951958, 2023). "Dong and colleague indicated that GATA3 contributed to the activation of a T helper 2 cell‐specific signalling pathway which was involved in carbon nanotubes‐induced pulmonary fibrosis." (PMID 27709831, 2017). "GATA3-tg mice developed exacerbated allergen-induced airway inflammation and airway remodeling, as well as bleomycin-induced pulmonary fibrosis, while GATA3-tg mice had less severe autoimmune glomerulonephritis." (PMID 24463292, 2014). "Our previous study demonstrated that the development of bleomycin-induced pulmonary fibrosis was significantly enhanced in mice overexpressing GATA3 with a lung Th2 cytokine bias." (PMID 20298567, 2010). "A previous study reported that miR-205 expression downregulated in the fibrotic lung tissue of bleomycin-induced pulmonary fibrosis mice, and that miR-205 may play a role in inhibiting the pulmonary fibrosis of mice by targeting GATA3." (PMID 33186919, 2020). "GATA3 was demonstrated to enhance the development of pulmonary fibrosis." (PMID 27709831, 2017). "In our model Tregs are marked by the expression of Gata3, a transcription factor established to play a cardinal role in Treg physiology during inflammation but not well defined in the context of lung fibrosis." (PMID 40631071, 2025). "Thus, GATA3-mediated Th2 cell differentiation and Th2 cytokine induction are an additional mechanism for aggravation of bleomycin-induced pulmonary fibrosis in mice lacking Nrf2." (PMID 20298567, 2010).